FGF23 (fibroblast growth factor 23)
Diseases named in the same sentence as FGF23 in open-access papers (continued):
Sharing a sentence is not in itself a finding about the gene and the disease.
dementia (12 papers, 2017 to 2025). Loss of intellectual abilities interfering with an individual's social and occupational functions. "A large study involving 1537 patients demonstrated that elevated FGF23 levels were associated with an increased risk of dementia and AD, suggesting a possible link between FGF23 and neurodegeneration [1047]." (PMID 40407975, 2025). "There are a number of possible explanations for the association we observed between FGF23 and dementia." (PMID 30830941, 2019). "We were unfortunately unable to measure serum klotho levels to determine if this protein modifies the association between serum FGF23 levels and dementia." (PMID 30830941, 2019). "On multivariable analysis, the highest quartile of FGF23, compared to the lowest quartile, was also associated with an increased risk of dementia (HR 1.75, 95% CI 1.01–3.03) and AD (HR 2.10, 95% CI 1.09–4.07)." (PMID 30830941, 2019). "Serum FGF23 levels are positively associated with the risk of developing dementia, suggesting that FGF23-related metabolic pathways may drive the development of dementia." (PMID 37962457, 2023). "Higher circulating FGF23 is associated with an increased risk of dementia, suggesting that FGF23-related biological pathways may play a role in the development of dementia." (PMID 30830941, 2019). "In the present study, we determined the association between serum FGF23 levels and cognitive performance, structural MRI brain measures predictive of dementia, and clinically confirmed, new-onset all-cause dementia and Alzheimer’s disease (AD), in a large, community-based, prospective cohort." (PMID 30830941, 2019). "We found that FGF23 was associated with an increased risk of dementia and AD." (PMID 30830941, 2019). "Third, FGF23 may increase the risk of dementia directly through its interaction with klotho, an anti-aging protein." (PMID 30830941, 2019). "Thus, the association between increased FGF23 levels and dementia could be explained by the effects of the anti-aging protein klotho and enhancing the effects of klotho could potentially protect against cognitive decline and dementia." (PMID 30830941, 2019). "However, it is unknown if serum FGF23 levels are associated with cognitive performance and late-life dementia in the general population." (PMID 30830941, 2019). "In contrast, decreased serum concentration of alpha-klotho, the co-receptor for FGF-23, has also been found in CKD and is related to higher risk of dementia and cerebral white matter disease." (PMID 32664677, 2020). "A test for linear trends across quartiles of FGF23 was significant for dementia (HR 1.20, 95% CI 1.02–1.41) and AD (HR 1.28, 95% CI 1.06–1.55)." (PMID 30830941, 2019). "Interestingly, FGF23 has been identified as a biomarker of aging, frailty, and age-related diseases including neurodegeneration (dementia) and sarcopenia." (PMID 34103575, 2021). "Higher FGF-23 was associated with incident dementia, but not with cognitive test score slopes or with structural brain disease." (PMID 33306729, 2020). "The C-statistic for the model of conventional risk factors for dementia was 0.81 (95% CI 0.77–0.84), with no significant change following the addition of FGF23 to the model." (PMID 30830941, 2019). "Higher serum FGF23 was associated with an increased risk of incident dementia, which was not accounted for by increased vascular risk factor burden or vascular measures of structural brain injury." (PMID 30830941, 2019). "We measured serum FGF23 levels in 1537 [53% women, mean age 68.7 (SD 5.7)] dementia-free Framingham Offspring participants at their 7th quadrennial examination (1998–2001), and followed these participants for the development of clinical all-cause dementia and Alzheimer’s disease (AD)." (PMID 30830941, 2019). "However, the association between FGF23 and dementia was not attenuated after adjusting for vascular risk factors, suggesting that the association is unlikely to be solely mediated through increased systemic vascular risk." (PMID 30830941, 2019).
dementia (continued). "While previous studies have reported an association between serum FGF23 and radiographic markers of cerebral small vessel disease and cognitive performance, there have been no studies to date looking at clinically confirmed dementia or AD." (PMID 30830941, 2019). "The strengths of our study are the inclusion of a population confirmed to be free of clinical dementia at baseline, the use of stringent surveillance procedures for detecting dementia, and inclusion of a large sample of participants with recorded serum FGF23 levels." (PMID 30830941, 2019). "FGF23-related biological pathways may play a role in the development of dementia." (PMID 30830941, 2019).
osteosarcoma (12 papers, 2012 to 2026). A usually aggressive malignant bone-forming mesenchymal neoplasm, predominantly affecting adolescents and young adults. "Bioinformatics analysis using the R2 database revealed that elevated FGF-23 expression is associated with increased metastasis and reduced overall survival in osteosarcoma patients." (PMID 41399365, 2026). "Following this, in the present study, we evaluated the specificity and practicality of FGF23 immunoreactivity as a specific diagnostic tool to differentiate UPSb tumours from osteosarcomas and dedifferentiated chondrosarcomas." (PMID 38397231, 2024). "In the present study, we evaluated the specificity and practicality of FGF23 immunoreactivity as a specific diagnostic tool to differentiate UPSb tumours from osteosarcomas and dedifferentiated chondrosarcomas." (PMID 38397231, 2024). "Increasing evidences have been indicated that FGF23 is associated with the biological behavior of malignant tumors, but its role in osteosarcoma and the specific mechanism need to be elucidated." (PMID 36604721, 2023). "Fibroblast growth factor-23 (FGF-23), a bone-derived hormone, has been implicated in tumor progression, but its role in osteosarcoma remains unclear." (PMID 41399365, 2026). "Our findings suggest that FGF-23 promotes osteosarcoma cell migration and metastasis by upregulating LOXL2 expression via activation of the ERK, p38, and JNK signaling pathways." (PMID 41399365, 2026). "In vitro experiments confirmed that treatment of osteosarcoma cells with FGF-23 increased LOXL2 mRNA and protein expression in a dose-dependent manner, while the effects on LOXL1 and LOXL3 were comparatively limited." (PMID 41399365, 2026). "Wound healing assays further demonstrated that FGF-23 enhanced osteosarcoma cell migration, an effect that was significantly inhibited by LOXL2 siRNA transfection." (PMID 41399365, 2026). "Online database analysis revealed that FGF-23 expression is significantly upregulated in metastatic osteosarcoma samples compared to primary tumors." (PMID 41399365, 2026). "Analysis of the GDC TARGET-OS cohort revealed a positive correlation between FGF-23 expression and metastatic phenotype in osteosarcoma patients." (PMID 41399365, 2026). "In this study, we sought to identify a mechanistic link between FGF-23 and the metastatic behavior of osteosarcoma cells, focusing on the miR-4463/LOXL2 axis and its effects in regulating the ERK, p38, and JNK signaling pathway." (PMID 41399365, 2026). "Together, these findings provide strong evidence that FGF-23 promotes osteosarcoma cell migration by specifically upregulating LOXL2 expression." (PMID 41399365, 2026). "Taken together, these findings suggest that FGF-23 exerts a pro-metastatic effect in osteosarcoma through ERK-, p38-, and JNK-mediated regulation of the miR-4463/LOXL2 axis." (PMID 41399365, 2026). "Wound healing and Transwell assays demonstrated a dose-dependent increase in the migratory capacity of osteosarcoma cells following FGF-23 treatment." (PMID 41399365, 2026). "Collectively, our findings suggest that these pathways play a key role in mediating FGF-23-driven osteosarcoma metastasis." (PMID 41399365, 2026). "In conclusion, this study demonstrates that FGF-23 promotes the migration and metastatic potential of osteosarcoma cells by upregulating LOXL2 expression through the suppression of miR-4463." (PMID 41399365, 2026). "Studies in the osteosarcoma cell line UMR106 showed that phosphate stimulated Fgf23 expression via ROS production." (PMID 38772920, 2024). "In contrast, osteosarcoma and dedifferentiated chondrosarcoma, both of which show low FGF23 expression, have high matrix mineralisation." (PMID 38397231, 2024). "The expression of FGF23 levels was low in osteosarcoma in terms of both cell positivity and the intensity of the immunostaining." (PMID 38397231, 2024).
osteosarcoma (continued). "In our previous study, increased FGF23 gene expression was coupled with the distinction between 14 UPSb and 16 osteosarcoma samples randomly chosen from the SRA bioproject PRJNA345424, which was revealed via unsupervised hierarchical clustering." (PMID 38397231, 2024). "Specifically, here, we detected a significant difference between UPSb and 10 osteosarcoma cases from the Royal Orthopaedic Hospital NHS Foundation Trust Tumour Bank in terms of FGF23 protein expression." (PMID 38397231, 2024). "Nevertheless, it should be mentioned that moderate FGF23 staining was detected in osteosarcoma samples, encompassing both large, atypical cells and osteoclast-like giant cells." (PMID 38397231, 2024). "Semiquantitative analysis based on the intensity of the immunoreactivity confirmed that FGF23 expression levels were significantly higher in UPSb tissues than in osteosarcoma and dedifferentiated chondrosarcoma tissues." (PMID 38397231, 2024). "In contrast, FGF23 staining was weak and patchy in tissue sections from both osteosarcoma and dedifferentiated chondrosarcoma." (PMID 38397231, 2024). "A semiquantitative analysis, considering the intensity of immunoreactivity, confirmed significantly elevated FGF23 expression levels in UPSb tissues compared to those observed in osteosarcoma and dedifferentiated chondrosarcoma tissues." (PMID 38397231, 2024). "We have previously identified that UPSb tumours have elevated mRNA levels of Fibroblast Growth Factor 23 (FGF23) transcripts compared to other sarcomas including osteosarcoma." (PMID 38397231, 2024). "The low level of FGF23 expression in dedifferentiated chondrosarcoma and osteosarcoma is consistent with the findings of a previous report." (PMID 38397231, 2024). "MiR-340-5p inhibitor partially reversed the inhibitory effect of si-FGF23 on the proliferation, migration and invasion of osteosarcoma cells." (PMID 36604721, 2023). "The purpose of this study is to investigate the effects of FGF23 on the proliferation, migration and invasion of osteosarcoma cells, and the possible molecular mechanisms." (PMID 36604721, 2023). "From this part of the results, it can be found that FGF23 can promote osteosarcoma cell migration, invasion and epithelial-mesenchymal transition (EMT)." (PMID 36604721, 2023). "FGF23 promotes osteosarcoma cell proliferation, migration and invasion by targeting miR-340-5p gene expression." (PMID 36604721, 2023). "FGF23 is highly expressed in osteosarcoma cells and can promote the ability of osteosarcoma cells to proliferate and migrate." (PMID 36604721, 2023). "Western blot was used to detect differences in FGF23 expression in osteosarcoma cells MG-63 and U2-OS and osteoblasts hFOB1.19." (PMID 36604721, 2023). "MPC cells express FGF23 in response to 1,25D, similar to osteosarcoma lines such as the rat osteoblast/osteocyte cell line UMR-10636,37." (PMID 34799645, 2021). "Our study demonstrates that TNFα upregulated Fgf23 transcript levels in UMR106 osteosarcoma-like cells." (PMID 29807981, 2018). "Beyond osteosarcoma, FGF-23 dysregulation has been reported in other bone-related conditions." (PMID 41399365, 2026). "Targeting FGF-23 or its downstream signaling cascades may offer a promising therapeutic approach for metastatic osteosarcoma." (PMID 41399365, 2026). "Given its established role in multiple bone-related pathologies and malignancies, FGF-23 may also be an important driver of osteosarcoma metastasis." (PMID 41399365, 2026). "Collectively, these findings suggest that FGF-23 enhances osteosarcoma cell migration in vitro and may contribute to the metastatic progression of osteosarcoma." (PMID 41399365, 2026). "Taken together, these findings suggest that FGF-23 promotes osteosarcoma cell migration and may contribute to metastasis through coordinated regulation of the miR-4463/LOXL2 axis via ERK, p38, and JNK signaling." (PMID 41399365, 2026).
osteosarcoma (continued). "Functional assays confirmed that FGF-23 enhances the migratory ability of osteosarcoma cells." (PMID 41399365, 2026). "Moreover, through the integration of this study with our previous research, the distinction in FGF23 expression between UPSb and OS becomes evident with two distinct cohorts of osteosarcoma." (PMID 38397231, 2024). "Further exploration of FGF23 expression in this osteosarcoma subtype and, potentially, other subtypes could enhance the investigation, especially considering the existence of various described osteosarcoma subtypes." (PMID 38397231, 2024). "FGF23 is highly expressed in osteosarcoma cells compared to hFOB1.19." (PMID 36604721, 2023). "FGF23 can target miR-340-5p to regulate the development and progression of osteosarcoma cells." (PMID 36604721, 2023). "The results of this study suggest that FGF23 may be an effective molecular target for the clinical treatment of osteosarcoma." (PMID 36604721, 2023). "Furthermore, pretreatment with ERK, p38, and JNK inhibitors or siRNAs reversed the FGF-23-induced suppression of miR-4463 and the increase in LOXL2 expression, indicating that the FGF-23/miR-4463/LOXL2 axis contributes to the regulation of osteosarcoma metastasis." (PMID 41399365, 2026). "However, the precise intermediate molecular mechanisms linking FGF-23 and miRNA regulation in osteosarcoma remain unclear." (PMID 41399365, 2026). "In parallel, the search for FGF23 expression in the complex osteosarcoma microenvironment, which has been recently highlighted by scRNA-seq investigations, could help with understanding if FGF23 is not expressed in any OS and associated normal subpopulation." (PMID 38397231, 2024). "Our results demonstrated that FGF-23 promotes LOXL2 expression and enhances osteosarcoma cell migration through activation of ERK, p38, and JNK signaling pathways, while simultaneously inhibiting miR-4463 expression." (PMID 41399365, 2026). "In our study, wound healing and qPCR assays showed that pretreatment of osteosarcoma cells with ERK, p38, or JNK inhibitors—or siRNAs targeting ERK, p38, or JNK—significantly reduced FGF-23-induced cell migration and LOXL2 expression." (PMID 41399365, 2026). "Experimental validation demonstrated that FGF-23 significantly downregulates miR-4463 expression while upregulating LOXL2, thereby promoting osteosarcoma cell migration." (PMID 41399365, 2026). "In the present study, pretreatment of osteosarcoma cells with a miR-4463 mimic reversed FGF-23-mediated LOXL2 expression downstream of ERK, p38, and JNK signaling, and suppressed the enhanced migratory ability of osteosarcoma cells in vitro." (PMID 41399365, 2026). "In vitro experiments further showed that FGF-23 significantly upregulates LOXL2 expression in 143B and MG63 osteosarcoma cells, while LOXL2 knockdown via small interfering RNA (siRNA) markedly reduces cell migration." (PMID 41399365, 2026). "In summary, this study demonstrates that FGF-23 suppresses miR-4463 synthesis through the ERK, p38, and JNK signaling cascade, thereby facilitating LOXL2-dependent migration in osteosarcoma cells." (PMID 41399365, 2026). "Pretreatment with specific inhibitors or siRNAs targeting ERK, p38, and JNK effectively suppressed FGF-23-induced LOXL2 expression and reduced osteosarcoma cell migration." (PMID 41399365, 2026). "In this study, we investigated the role of miRNAs in FGF-23-induced LOXL2 expression and osteosarcoma cell migration." (PMID 41399365, 2026). "To further validate the functional role of FGF-23, we generated osteosarcoma cell lines (143B/FGF-23 and MG63/FGF-23) that stably overexpress FGF-23." (PMID 41399365, 2026). "In the present study, we demonstrated that the growth factor FGF-23 activates ERK, p38, and JNK signaling, leading to upregulation of LOXL2 and enhanced migratory capacity of osteosarcoma cells." (PMID 41399365, 2026).
osteosarcoma (continued). "FGF23-overexpressing adenoviruses and FGF-silencing plasmids were transfected into osteosarcoma cells, and transfection efficiency was verified using Western blot." (PMID 36604721, 2023). "The same group reported an increase in bone FGF23 protein abundance and in FGF23 expression in MG53 cells, a human osteosarcoma cell line, when incubated with dexamethasone." (PMID 34659120, 2021). "Kaplan-Meier survival analysis demonstrated a negative correlation between FGF-23 expression levels and postoperative survival duration in osteosarcoma patients." (PMID 41399365, 2026). "Moreover, fibroblast growth factor-23 (FGF-23) has been shown to regulate miRNA expression, with studies indicating that FGF-23 enhances miR-340-5p expression, thereby influencing osteosarcoma cell proliferation, migration, and invasion." (PMID 41399365, 2026). "Stimulation of osteosarcoma cells with various concentrations of FGF-23 did not affect cell viability." (PMID 41399365, 2026). "Functional assays using Transwell and wound healing methods revealed that FGF-23 overexpression significantly increased the migratory capacity of osteosarcoma cells without affecting cell proliferation." (PMID 41399365, 2026). "Additionally, Western blotting showed that FGF-23 stimulation increased ERK, p38, and JNK phosphorylation in osteosarcoma cells." (PMID 41399365, 2026). "Investigating the interplay between FGF-23 and LOXL2 in osteosarcoma may provide new mechanistic insights and identify potential therapeutic targets to inhibit malignant progression and improve clinical outcomes." (PMID 41399365, 2026). "It's worth noting that earlier studies indicating direct regulation of Fgf23 by ROS were conducted in UMR106 cells, an osteosarcoma cell line that may not reflect the physiology of Fgf23 regulation in osteocytes." (PMID 38772920, 2024). "To date, however, there is no relevant report on whether FGF23 is able to regulate osteosarcoma growth and migration." (PMID 36604721, 2023). "Moreover, the osteosarcoma cell line UMR106 is often used, but as this is a cancerous cell line, FGF23 regulation might be altered/deranged." (PMID 33716961, 2021). "Therefore, the phenotypes associated with UPSb may be attributed to the overexpression of FGF23, as these are not seen in osteosarcoma and dedifferentiated chondrosarcoma, which have low FGF23 levels." (PMID 38397231, 2024).